IDH1-AS1 (IDH1 antisense RNA 1)
Synonyms: IADMP
Gene: Long non-coding RNA gene on chromosome 2 (208,254,173 to 208,256,233, forward strand). Ensembl gene ENSG00000231908.
Diseases named in the same sentence as IDH1-AS1 in open-access papers:
IDH1-AS1 is named in the same sentence as 1 disease in open-access papers, as found by Europe PMC text mining. Sharing a sentence is not in itself a finding about the gene and the disease. The quoted sentences say what the papers report.
epithelial ovarian cancer (1 paper, 2023). "Long noncoding RNA (lncRNA) IDH1 antisense RNA 1 (IDH1-AS1) is involved in the progression of multiple cancers, but its role in epithelial ovarian cancer (EOC) is unknown." (PMID 37981573, 2023).